RSPO2 (R-spondin 2)
Description:
Activator of the canonical Wnt signaling pathway by acting as a ligand for LGR4-6 receptors. Upon binding to LGR4-6 (LGR4, LGR5 or LGR6), LGR4-6 associate with phosphorylated LRP6 and frizzled receptors that are activated by extracellular Wnt receptors, triggering the canonical Wnt signaling pathway to increase expression of target genes. Also regulates the canonical Wnt/beta-catenin-dependent pathway and non-canonical Wnt signaling by acting as an inhibitor of ZNRF3, an important regulator of the Wnt signaling pathway. During embryonic development, plays a crucial role in limb specification, amplifying the Wnt signaling pathway independently of LGR4-6 receptors, possibly by acting as a direct antagonistic ligand to RNF43 and ZNRF3, hence governing the number of limbs an embryo should form.
Synonyms: MGC35555; CRISTIN2; HHRRD; TETAMS2
Tractability: Small molecule: a structure with a bound ligand is known. Antibody: its Gene Ontology location is reachable by antibodies, with high confidence; UniProt places it where antibodies can reach, with medium confidence; UniProt predicts a signal peptide or a membrane-spanning region.
Gene: Protein-coding gene on chromosome 8 (107,899,316 to 108,083,790, reverse strand). Ensembl gene ENSG00000147655.
Subcellular location: Secreted
Pathways (Reactome):
Signal Transduction: Regulation of FZD by ubiquitination
Gene Ontology:
Molecular function: protein binding; signaling receptor binding; BMP receptor binding; heparin binding
Biological process: limb development; positive regulation of Wnt signaling pathway; positive regulation of canonical Wnt signaling pathway
Cellular component: extracellular region; non-collagenous component of interstitial matrix; cell surface
Genetic constraint (gnomAD): Loss-of-function variants: 12 observed, 29.1 expected, observed/expected ratio (o/e) 0.41, 90% interval 0.26 to 0.67. The upper end of that interval is the gene's LOEUF score, 0.67, which puts it in group 2 of 6, group 1 being the genes least tolerant of losing a copy. Missense variants: 260 observed, 305.02 expected, observed/expected ratio (o/e) 0.85, 90% interval 0.77 to 0.94. Synonymous variants: 104 observed, 98.42 expected, observed/expected ratio (o/e) 1.06, 90% interval 0.9 to 1.24.
Homologues: Orthologues: chimpanzee RSPO2 (99% identical), macaque RSPO2 (99% identical), rabbit RSPO2 (98% identical), mouse Rspo2 (96% identical), pig RSPO2 (96% identical), rat Rspo2 (95% identical), guinea pig RSPO2 (87% identical), dog RSPO2 (84% identical), tropical clawed frog rspo2 (84% identical), zebrafish rspo2 (73% identical). Paralogues in human: RSPO3 (44% identical), RSPO1 (40% identical), RSPO4 (39% identical).
Diseases named in the same sentence as RSPO2 in open-access papers:
RSPO2 is named in the same sentence as 85 diseases in open-access papers, as found by Europe PMC text mining. Sharing a sentence is not in itself a finding about the gene and the disease. The quoted sentences say what the papers report.
colon cancer (18 papers, 2013 to 2026). "For example, RSPO2 inhibits the development of colon cancer through suppressing Wnt/β-catenin signaling." (PMID 41522353, 2026). "Originally in colon cancer, but also later in other cancer types, the RSPO2 and RSPO3 gene fusion product has been reported to correlate with a poor prognosis and survival." (PMID 37998393, 2023). "RSPO2 and RSPO3 mutations are found in approximately 10% of colon cancers and occur in a mutually exclusive manner with APC mutations." (PMID 37048063, 2023). "It has been reported that RSPO2 regulates hepatocellular carcinoma, colon cancer progression, osteoblast activity, facial morphogenesis, and maturation of ovarian follicles by activating canonical WNT/β-catenin signaling." (PMID 34847079, 2022). "In colon cancer, RSPO2 and RSPO3 gene fusions have been proposed to potentiate Wnt/β‐catenin signaling, providing a mutational alternative for classical APC and CTNNB1 mutations." (PMID 36106661, 2022). "These included an ovarian tumor with RSPO1, pancreatic and colon tumors with RSPO2, and lung and CRC tumors with RSPO3 overexpression." (PMID 34663878, 2021). "Two previous studies found RSPO2 transcripts fusions and RSPO2 over-expression in colon cancer patients." (PMID 30250044, 2018). "RSPO2 is highly expressed in colon cancer stem cells and promotes the invasion of CRC cells through enhancing epithelial-mesenchymal transition." (PMID 28350845, 2017). "In just one year after the initial discovery of RNF43 mutations in IPMN and MCN, recurrent RSPO2 and RSPO3 translocations were identified in 3.0% and 8.0% of colon cancer, respectively." (PMID 27338477, 2016). "Next, we examined the expression of LGR4 in human colon cancers and their normal adjacent tissues with 7E7 given the finding of recurrent RSPO2/3 gene fusions in human colon cancer." (PMID 24205130, 2013). "RSPO1 stimulation of LGR4 potentiates Wnt signaling which is generally oncogenic, and overexpression of RSPO2 and RSPO3 is associated with carcinogenesis in human colon cancer as well as in mouse models of breast and colon cancer." (PMID 24205130, 2013). "It was also the only receptor that was consistently expressed in colon tumors with RSPO2 or RSPO3 gene fusions." (PMID 24205130, 2013). "Additionally, WNT974 treatment regressed murine intestinal tumours harbouring either Rspo2 or Rspo3 fusion mutations, whilst another PORCNi suppressed the growth of RSPO3-mutant patient-derived colon cancer organoids in a xenograft model." (PMID 37048063, 2023). "However, RSPO2 exhibited two contradictory roles in colon cancer." (PMID 36645115, 2023). "It was found that overexpression of RSPO2 and RSPO3 was presented by 4-10% of colon subjects and recurrent R-spondin fusions in colon cancer activate the Wnt signaling and increase the tumorigenesis." (PMID 37228491, 2023). "First, RSPO2 and RSPO3 gene fusions with concomitant enhanced expression have been identified in colon cancer patients, and proposed as an alternative driver of Wnt/β-catenin hyperactivation that earmarks cancer in the colorectal tract." (PMID 34663878, 2021). "Remarkably, recurrent, gain-of-expression gene fusion of RSPO2 (to EIF3E) and RSPO3 (PTPRK) were found in ~10% of human colon cancers." (PMID 24205130, 2013). "used RNA-SEQ to analyze 70 pairs of colon cancer tumors and their adjacent non-cancer tissues and identified a plurality of fusion transcripts involving RSPO2 and RSPO3, where the two transcriptions appeared together in patients with colon cancer in colon cancer." (PMID 36645115, 2023). "Indeed, the expression of RSPO2 and RSPO3 in colon tumor samples containing such fusions is significantly elevated compared with tumor samples without the fusions." (PMID 27338477, 2016). "In addition, RSPO2 and RSPO3 mRNAs are significantly overexpressed in a subset of colon cancer." (PMID 37998393, 2023).
colon cancer (continued). "Intriguingly, two previous studies demonstrated that RSPO2 inhibits colorectal cancer growth through unique LGR5-mediated Wnt/β-catenin signaling negative feedback mechanism, and RSPO2-mediated suppression of noncanonical Wnt signaling also exerted an inhibitory effect on colon tumor metastasis." (PMID 36217544, 2022). "Indeed, recurrent activating RSPO2 and RSPO3 gene fusions were found to occur in 10% of human colon tumors and a recent follow-up study targeting RSPO3 in a RSPO3-fusion tumor xenograft model was shown to downregulate genes expressed in the stem cell compartment and inhibit tumor growth." (PMID 27046199, 2016). "Following up on the initial discovery of RSPO gene fusions in CRC patients, other studies identified additional gene fusions of RSPO2 with PIEZO1, NRIPI and PRR15L and moreover, reported RSPO gene fusions to typically occur in traditional serrated adenoma (TSA) rather than conventional colon tumors." (PMID 34663878, 2021).
colorectal cancer (16 papers, 2014 to 2024). A primary or metastatic malignant neoplasm that affects the colon or rectum. "Moreover, a gain in RSPO2 or RSPO3 levels is evident in a subpopulation of colorectal cancer patients, caused either by stromal overexpression or by specific gene fusions, among which EIF3E–RSPO2 and PTPRK–RSPO3 occur mutually exclusively with classical APC and CTNNB1 driver mutations." (PMID 36106661, 2022). "As reported, RSPO2 suppressed colorectal cancer progression by negatively regulating Wnt/β-catenin signaling through an LGR5-dependent feedback mechanism." (PMID 32018224, 2020). "R-Spondin fusions, including protein tyrosine phosphatase receptor type K-R-Spondin (PTPRK-RSPO3) and eukaryotic transplation initiation factor subunit E/R-Spondin 2 (EIF3E-RSPO2) fusion, have been reported in 4–10 colorectal cancers." (PMID 29652830, 2018). "It is shown that RSPO2 is silenced in colorectal cancer due to promoter hypermethylation, and that exogenous RSPO2 suppresses β-catenin signaling through stabilization of ZNRF3 on the plasma membrane." (PMID 27338477, 2016). "Taken together, RSPO2/3 translocations and RNF43 mutations are enriched in distinct subtypes of colorectal cancer in terms of mismatch repair." (PMID 27338477, 2016). "Rspo2 was identified as a colorectal cancer candidate gene in a transposon-based genetic screen in mice." (PMID 27338477, 2016). "Although the frequency is lower than that reported in the previous study, the Japanese colorectal cancer samples with RSPO2/3 fusions are similarly positive for the expression of mismatch repair proteins and have the wild-type APC allele." (PMID 27338477, 2016). "The role of RSPO2 in colorectal cancer is arguable according to the published article." (PMID 28350845, 2017). "RSPO2 and RSPO3 translocations appear to be mutually exclusive with APC mutations, consistent with the idea that the Wnt/β–catenin pathway needs to be activated one way or another in colorectal cancers." (PMID 25208913, 2014). "Three samples had elevated RSPO2 mRNA levels, including GA007 (Gastric cancer 007), GA3055 (Gastric cancer 3055), and CR3056 (Colorectal cancer 3056)." (PMID 30250044, 2018). "Moreover, they determined that the RSPO2 overexpression was the result of a deletion-mediated gene fusion between exon 1 of EIF3E and exon 2 of RSPO2, the same as described in colorectal cancer." (PMID 34771683, 2021). "Notably, RSPO2 and RSPO3 are overexpressed by chromosome translocations in a subset of colorectal cancers; this translocation product markedly stimulates Wnt/β-catenin signalling." (PMID 25208913, 2014). "Previous studies have shown that RSPO2, but not other members of the RSPO protein family, has tumour suppressor activity in colorectal cancer." (PMID 37612734, 2023).
breast cancer (14 papers, 2012 to 2025). A primary or metastatic malignant neoplasm involving the breast. "We found that a quarter of breast cancer patients harbor RSPO2/RSPO3 copy number amplifications, which are associated with lack of steroid hormone receptor expression and reduced patient survival." (PMID 36106661, 2022). "Adding to this, we found that a quarter of breast cancer patients harbor RSPO2 or RSPO3 copy number amplification, which is associated with high tumor grade, ER and PR negative status, and reduced survival, indicating the clinical relevance of RSPO." (PMID 36106661, 2022). "Moreover, we found that a quarter of breast cancer patients harbor RSPO2/RSPO3 copy number amplification, which is associated with worse prognosis and lack of steroid hormone receptor expression, restricting therapeutic options." (PMID 36106661, 2022). "Among the RSPO members, copy number amplifications of the RSPO2 gene occurred most frequently, being present in 23% (503/2,173) of breast cancer patients." (PMID 36106661, 2022). "Taken together, these data indicate that over a quarter of breast cancer patients harbor RSPO2 or RSPO3 amplification, leading to a reduced clinical outcome." (PMID 36106661, 2022). "In summary, we report that a quarter of breast cancer patients harbor RSPO2/RSPO3 copy number gains, and these patients have a worse prognosis, whilst providing in vivo evidence that RSPO3 drives poorly differentiated invasive breast cancer in mice." (PMID 36106661, 2022). "In breast cancer patients, RSPO2, RSPO3, and RSPO4 overexpression has been reported, which is associated with hormone receptor‐negative tumor status and for RSPO2 also with reduced patient survival." (PMID 36106661, 2022). "This was further supported by experiments where injection of cell lines overexpressing Rspo2 or Rspo3 in the mouse mammary gland resulted in mammary tumor formation, and distant metastases in case of Rspo2." (PMID 34663878, 2021). "For example, although Rspo2 and Wnt1 are both found as common integration sites in the MMTV-induced mouse mammary tumor model, Rspo2- and Wnt1-transformed mammary epithelial cells behave differently in vivo." (PMID 27338477, 2016). "Importantly, breast cancer patients harboring RSPO2 or RSPO3 copy number amplification showed a significantly reduced overall survival." (PMID 36106661, 2022). "Notably, the two cell lines HBcc-15 and BT549 that are derived from breast cancer patients do have EIF3E-RSPO2 gene fusions, and siRNA-mediated inhibition of RSPO2 in BT549 cells was shown to reduce the proliferation of this TNBC cell line." (PMID 34663878, 2021). "In breast cancer, DKK1 can be stimulated by the upstream RSPO2–RANKL–LGR4–Gαq–β‐catenin pathway, which promotes the recruitment of osteoclast precursor cells and ultimately promotes the bone metastasis of breast cancer tumors." (PMID 38525111, 2024). "As patient data suggested a pro‐tumorigenic role for RSPO2 and RSPO3 in breast cancer, we aimed to determine the oncogenic potential of RSPO in breast cancer." (PMID 36106661, 2022). "To systematically evaluate the role of RSPO2 and RANKL in the premetastatic niche, we used immunocompetent mice with the mouse mammary cancer cell line 4T1." (PMID 34847079, 2022). "Rspo2 and Rspo3 were firstly identified as sites of integration for MMTV-induced mammary tumors in mice, which suggest a role of Rspos as breast cancer oncogenes." (PMID 30337838, 2018). "Rspo2 and Rspo3 were identified as sites of integration for mouse mammary tumor virus (MMTV)-induced mammary tumors." (PMID 27338477, 2016). "Similarly, R-spondin 2 (RSPO2) and RANKL, secreted from breast cancer cells, are involved in the recruitment of osteoclast progenitors and formation of osteoclastic pre-metastatic niche." (PMID 35994202, 2022).
breast cancer (continued). "Overexpression of RSPO2, RSPO3, and RSPO4 has been reported in breast cancer patients, in particular in triple‐negative tumors, where enhanced RSPO2 expression was associated with reduced metastasis‐free survival." (PMID 36106661, 2022).
osteoarthritis (13 papers, 2017 to 2025). A noninflammatory degenerative joint disease occurring chiefly in older persons, characterized by degeneration of the articular cartilage, hypertrophy of bone at the margins and changes in the synovial membrane. "An earlier study by Zhang also revealed that as an important protein secreted by M1 macrophages, Rspo2 exacerbates the development of experimental osteoarthritis, implicated its potential role in OA treatment." (PMID 37354487, 2023). "M1 polarization was associated with the release of R-spondin-2 and the activation of β-catenin signaling, which could exacerbate the progression of osteoarthritis." (PMID 35473522, 2023). "PRG4 synovial fibroblasts secrete R-spondin-2 to promote the occurrence and development of osteoarthritis." (PMID 40470275, 2025). "Rspo2 was also proved to play markedly roles in pathological crosstalk among macrophages, chondrocytes and synovial fibroblasts in a post-traumatic osteoarthritis setting." (PMID 37354487, 2023). "The article titled “Synovial macrophage M1 polarisation exacerbates experimental osteoarthritis partially through R-spondin-2”, published in 2018, ranked first (strength = 16.3)." (PMID 36268031, 2022). "Low levels of R-spondin-2 (Rspo-2), a Wnt/β-catenin signaling pathway agonist, and high level of sclerostin, have been found in primary human osteoarthritis osteoblast cultures." (PMID 28617323, 2017). "Several lines of evidence indicate that there may be some relationships between Rspo2 and osteoarthritis." (PMID 37354487, 2023). "Prg4+ synovial fibroblasts expressed Rspo2, which may contribute to pathological crosstalk between joints in the post-traumatic osteoarthritis model." (PMID 38002046, 2023). "Our previous study had demonstrated that Rspo2 secreted by synovium could disrupt cartilage homeostasis during osteoarthritis progression." (PMID 37946278, 2023). "In addition, a destabilization of the medial meniscus (DMM)-induced OA model was used in vivo to address the roles of astaxanthin and Rspo2 in the development of osteoarthritis, with a view to detecting critical approaches for the treatment of osteoarthritis." (PMID 37354487, 2023). "In addition, enhanced expression of LGR5 and RSPO2 was detected in chondrocytic differentiation of human chondrocytes in advanced stage of osteoarthritis, while elevated expression of LGR6 and RSPO1 was observed in osteogenic differentiation of SaOS‐2 cells." (PMID 35668632, 2022).
hepatocellular carcinoma (8 papers, 2020 to 2024). A malignant tumor that arises from hepatocytes. "Several other studies reported subsets of hepatocellular carcinoma that harbor RSPO2 copy number amplifications or enhanced RSPO2 mRNA expression associated with Wnt/β-catenin activation." (PMID 34663878, 2021). "In hepatocellular carcinoma (HCC) cell lines microRNA-493 suppressed tumor cell growth by targeting TEM8/ANTXR1 and R-Spondin 2 (RSPO2) and decreasing activation of the Wnt/β-catenin signaling pathway." (PMID 36090051, 2022). "Additionally, RSPO2 promotes proliferation and migration through the WNT/β-catenin pathway in human hepatocellular carcinoma and positively regulates skeletal muscle formation." (PMID 33807555, 2021). "In addition, RSPO2 promotes proliferation and migration through the WNT/β-catenin pathway in human hepatocellular carcinoma and positively regulates skeletal muscle formation." (PMID 33807916, 2021).